APOB (apolipoprotein B)
Diseases named in the same sentence as APOB in open-access papers (continued):
Sharing a sentence is not in itself a finding about the gene and the disease.
celiac disease (2 papers, 2012 to 2016). An autoimmune genetic disorder with an unknown pattern of inheritance that primarily affects the digestive tract. "Compared to a normal population, patients with celiac disease have lower cholesterol, lower triglycerides, lower apolipoprotein B, lower fibrinogen, and higher HDL." (PMID 23094165, 2012). "HSP90AA1, MKKS, EZR, HSPA14, APOB and CAD are proteins that involved in protein networks of celiac disease and have been determined as seeds." (PMID 27895852, 2016).
cerebrotendinous xanthomatosis (2 papers, 2017 to 2024). Cerebrotendinous xanthomatosis (CTX) is an anomaly of bile acid synthesis characterized by neonatal cholestasis, childhood-onset cataract, adolescent to young adult-onset tendon xanthomata, and brain xanthomata with adult-onset neurologic dysfunction. "For example, apoB/LDL was found or obviously elevated in CSF collected from patients with subarachnoid hemorrhage, cerebrotendinous xanthomatosis, or tuberculous meningitis." (PMID 28800073, 2017).
chronic hepatitis B (2 papers, 2010 to 2018). "Because lipid metabolism and cancer are tightly integrated, chronic hepatitis B virus infection may decrease APOB levels and eventually cause HCC." (PMID 30429453, 2018).
chronic obstructive pulmonary disease (2 papers, 2018 to 2022). A chronic and progressive lung disorder characterized by the loss of elasticity of the bronchial tree and the air sacs, destruction of the air sacs wall, thickening of the bronchial wall, and mucous accumulation in the bronchial tree. "In addition, variation within the GSC has been associated with complex non-Mendelian traits, ranging from educational attainment to forced expiratory volume in chronic obstructive pulmonary disease to apolipoprotein B levels." (PMID 36118898, 2022).
co-infection (2 papers, 2023 to 2024). "The table presents measures of interaction between HPV and Fungi co-infection on cervical lesions, adjusted for age, pregnancy, parity, apolipoprotein A1, apolipoprotein B, total cholesterol, and triglyceride." (PMID 39257614, 2024). "We observed within‐host diversity and instances of co‐infection, and highlight further examples of structural variation and apolipoprotein B editing complex‐driven micro‐evolution in the current MPXV outbreak." (PMID 37565686, 2023).
deficiencies (2 papers, 2021 to 2024). "Fifth, another mutation in FH, ApoB, did not exert an important effect on thiamine and vitamin D deficiencies." (PMID 39502567, 2024).
endometriosis (2 papers, 2024 to 2025). The growth of functional endometrial tissue in anatomic sites outside the uterine body. "Except for TG, previous studies have reported enriched ApoB mRNA Editing Enzyme Catalytic Subunit (APOBEC) signature mutations were higher in endometriosis patients, indicating APOBEC-mediated mutagenesis might drive genomic heterogeneity in endometriosis." (PMID 38627726, 2024). "We compared endometriosis status, stage (I/II vs III/IV), and typology to no endometriosis using adverse lipid thresholds (total cholesterol ≥200 mg/dL, HDL <50 mg/dL, LDL ≥100 mg/dL, triglycerides ≥175 mg/dL, non-HDL ≥130 mg/dL, VLDL ≥30 mg/dL, ApoA1 <125 mg/dL, and ApoB ≥120 mg/dL)." (PMID 41407106, 2025).
esophageal squamous cell carcinoma (2 papers, 2023). Esophageal squamous cell carcinoma (ESCC) is a type of esophageal carcinoma (EC) that can affect any part of the esophagus, but is usually located in the upper or middle third. "The apolipoprotein B mRNA editing enzyme catalytic polypeptide (APOBEC) mutagenesis is prevalent in esophageal squamous cell carcinoma (ESCC)." (PMID 37215984, 2023).
glioma (2 papers, 2021 to 2023). A benign or malignant brain and spinal cord tumor that arises from glial cells (astrocytes, oligodendrocytes, ependymal cells). "Our own work identified APOA1 and APOA4 in the proteomic analyses of EVs derived from human medulloblastoma cell lines and murine glioma cells, with APOB and APOE identified in EVs from other tumor cell lines (Graner, unpublished data)." (PMID 34360613, 2021).
glomerulosclerosis (2 papers, 2020 to 2025). A hardening of the kidney glomerulus caused by scarring of the blood vessels. "In contrast, the pathogenic effects of LDL-C/ApoB are long-term and cumulative, with the main pathological changes likely manifesting as more advanced and extensive damage, such as glomerulosclerosis and renal interstitial fibrosis." (PMID 41430991, 2025).
homozygous familial hypercholesterolemia (2 papers, 2022 to 2024). "It inhibits apolipoprotein B-100 and increases the survival of patients with a rare genetic disease called homozygous familial hypercholesterolemia (HoFH)." (PMID 38534656, 2024).
hyperandrogenism (2 papers, 2019 to 2023). Excessive secretion of androgens from the adrenal glands or gonads. "In euthyroid PCOS patients, TSH, TG, TC, LDL-c, and apoB level increased from non-hyperandrogenism (nonHA) to HA group (all p < 0.05)." (PMID 31024459, 2019).
Hyperbilirubinemia (2 papers, 2022 to 2026). An increased amount of bilirubin in the blood. "In fully adjusted models, elevated TC (≥5.2 mmol/L), TG (≥1.7 mmol/L), LDL-C (≥3.4 mmol/L), and ApoB (≥1.2 g/L) levels were significantly associated with a lower hyperbilirubinemia risk." (PMID 41598393, 2026). "Hyperbilirubinemia was also associated with lower TC, TG, LDL-C, and ApoB levels, as well as the ApoB/ApoA1 ratio." (PMID 41598393, 2026). "Hyperbilirubinemia was also negatively associated with TC (p < 0.0001), TGs (p < 0.0001), LDL-C (p = 0.0061), very LDL-C (VLDL-C; p = 0.0043), and apolipoprotein B (ApoB; p < 0.0001) levels, as well as the ApoB/apolipoprotein A1 (ApoA1) ratio (p = 0.0003)." (PMID 41598393, 2026). "Hyperbilirubinemia significantly reduced serum TC, TG, LDL-C, and ApoB levels, as well as the ApoB/ApoA1 ratio." (PMID 41598393, 2026).
Hypofibrinogenemia (2 papers, 2020 to 2024). Decreased concentration of fibrinogen in the blood. "We in fact presented a case of a child with hypofibrinogenemia due to the Aguadilla mutation and severe hypobetalipoproteinaemia demonstrating that both fibrinogen and apolipoprotein B accumulated in the same endoplasmic reticulum inclusions despite the latter protein was not mutated." (PMID 33260935, 2020).
Hypoinsulinemia (2 papers, 2013 to 2023). A decreased concentration of insulin in the blood. "This may have been caused by the increased influx of fatty acids into the liver due to hypoinsulinemia, resulting in the accumulation of triglycerides in the liver in addition to decreased lipoprotein secretion capacity of the liver due to apolipoprotein B synthesis deficiency." (PMID 37655263, 2023).
liver failure (2 papers, 2011 to 2017). A liver disease characterized by the liver losing or has lost all of its function. "In our previous animal experiment, we found a disorder of lipid metabolism in liver failure mouse models, and the expression of some apolipoproteins (such as apoA-V, apoA-I, apoB, etc.)were significantly declined." (PMID 28358016, 2017).
lung adenocarcinoma (2 papers, 2020 to 2023). A carcinoma that arises from the lung and is characterized by the presence of malignant glandular epithelial cells. "APOC3 inhibition decreased the lung adenocarcinoma (LUAD) risk (OR 0.60, 95% CI 0.43–0.84, p = 0.039) but increased SCLC risk (OR 2.18, 95% CI 1.17–4.09, p = 0.029) via ApoB reduction by 1 SD." (PMID 38034491, 2023). "The preferential APOBEC (apolipoprotein B mRNA editing enzyme catalytic polypeptide-like)-induced hypermutation was observed in transformed SCLCs, whereas EGFR T790M-positive lung adenocarcinoma had rare APOBEC-associated mutations." (PMID 32762742, 2020).
Lyme disease (2 papers, 2020 to 2021). Lyme disease (named after the towns in the USA where the disease was first identified) is a bacterial infection caused by Borrelia burgdorferi. "Previous studies identified peptides from annexin A2, apolipoprotein B-100, thymidine phosphorylase (endothelial cell growth factor), and stromelysin-2 (matrix metalloproteinase 10) as targets of autoreactive T cells in a subset of human Lyme disease patients." (PMID 33043033, 2020).
lymph node metastases (2 papers, 2020 to 2025). "Seven optimal survival-related factors—TC/HDL > 10.08, apolipoprotein B > 0.9 g/L, lipoprotein> 72 mg/L, lymph node metastasis, radical cure, CA199 > 37 U/mL, and tumor differentiation —were included to construct the prognostic nomogram." (PMID 33036576, 2020). "The univariable analysis demonstrated that BMI, jaundice, lymph node metastasis, intrahepatic involvement, extrahepatic involvement, tumor differentiation, radical cure, R0, TG, HDL, TC/HDL, TG/HDL, ApoA1, ApoB, lipoprotein, albumin, GGT, ALP, TBIL, CA199 were associated with OS (P < 0.05)." (PMID 33036576, 2020). "And lymph node metastasis (P = 5.88 × 10− 7), tumor differentiation (P = 0.023), radical cure (P = 4.87 × 10− 7), R0 (P = 0.025), TC/HDL (P = 0.049), ApoB (P = 7.12 × 10− 7), lipoprotein (P = 1,12 × 10− 6), CA199 (P = 0.007) were shown to determine the OS." (PMID 33036576, 2020).
malignant melanoma (2 papers, 2022 to 2024). "Similarly decreases of several apolipoproteins (APOB, APOE, APOM) in nonresponding patients have also been reported as prognostic markers for malignant melanoma." (PMID 38777088, 2024).
myocardial ischemia (2 papers, 2015 to 2025). A disorder of cardiac function caused by insufficient blood flow to the muscle tissue of the heart. "Then the RCS analysis was used to evaluate the nonlinear relationship in this model, and the result suggested that there was a linear association between ApoB and the HR of myocardial ischemia occurrence, and the HR increased in the interval of ApoB value between 0.6 an 1.3." (PMID 40678973, 2025). "Results demonstrated that age, HER2, TG, ApoB, and Lp(a) were statistically significant factors in affecting myocardial ischemia occurrence." (PMID 40678973, 2025). "This study constructed a clinical prediction model using three key factors (ApoB, age, and HER2) for myocardial ischemia incidence based on the multivariable regression analysis." (PMID 40678973, 2025). "Plasma lipid disorders were induced by myocardial ischemia, with manifestation of up-regulation of triglyceride (TG), low density lipoprotein (LDL), Apolipoprotein B (Apo-B) and 3-hydroxy-3-methyl glutaryl coenzyme A reductase (HMGCR)." (PMID 25885422, 2015).
non-small cell lung carcinoma (2 papers, 2023 to 2025). A group of at least three distinct histological types of lung cancer, including non-small cell squamous cell carcinoma, adenocarcinoma, and large cell carcinoma. "Genetic variants of APOB and CDH13 in the cholesterol pathway have been shown to affect survival in non-small cell lung cancer by modulating gene expression." (PMID 40696350, 2025). "Previous study found APOB gene variation associated with the survival rate of non-small cell lung cancer, but no research reported the correlation between APOB gene and BPD, which is worth digging into." (PMID 36757497, 2023).
osteosarcoma (2 papers, 2022 to 2024). A usually aggressive malignant bone-forming mesenchymal neoplasm, predominantly affecting adolescents and young adults. "Univariate Cox regression analysis showed that APOB and APOE were significantly associated with OS in patients with osteosarcoma." (PMID 38212768, 2024). "Recent studies have found that APOC1 promotes osteosarcoma progression through binding to MTCH2, and preoperative APOB/APOA1 has been identified as an independent prognostic factor for osteosarcoma in children and adolescents." (PMID 38212768, 2024). "Further subgroup analysis was performed to investigate the prognostic value of PAR, PLR, LDL-C/HDL-C, and ApoB/ApoA1 in children and adolescent patients with osteosarcoma stratified by Enneking stage." (PMID 35086516, 2022). "More significantly, we confirmed for the first time that preoperative PAR and ApoB/ApoA1 can be identified as independent prognostic factors for OS in children and adolescents with osteosarcoma." (PMID 35086516, 2022). "More significantly, we confirmed that preoperative PAR and ApoB/ApoA1 can be identified as independent prognostic factors for OS in children and adolescents with osteosarcoma." (PMID 35086516, 2022). "Preoperative PAR and ApoB/ApoA1 can be used as promising predictors in children and adolescents with osteosarcoma to help clinicians recognize patients with an increased risk of poor prognosis." (PMID 35086516, 2022). "Herein, this retrospective study investigated the prognostic value of preoperative PAR, PLR, LDL-C/HDL-C, and ApoB/ApoA1 in children and adolescents with osteosarcoma." (PMID 35086516, 2022). "In univariate and multivariable analyses, preoperative PAR and ApoB/ApoA1 were identified as independent prognostic factors for OS in children and adolescents with osteosarcoma." (PMID 35086516, 2022). "In summary, this study found that osteosarcoma patients with relatively high preoperative PAR and ApoB/ApoA1were associated with shorter OS." (PMID 35086516, 2022). "Based on this, interventions or drugs aimed at reducing the ratio of PAR and ApoB/ApoA1 might be a potentially effective strategy to improve the prognosis of osteosarcoma." (PMID 35086516, 2022). "Whereas, as new indicators for evaluating OS, the potential mechanism of serum PAR and ApoB/ApoA1 to predict the survival outcomes of osteosarcoma remains unclear." (PMID 35086516, 2022). "Osteosarcoma patients in high PAR group (> 4.41) and high ApoB/ApoA1 group (> 0.82) experienced significantly shorter overall survival compared with those in low PAR group (≤ 4.41) and low ApoB/ApoA1 group (≤ 0.82)." (PMID 35086516, 2022).
paroxysmal AF (2 papers, 2022). "Patients with paroxysmal AF had significantly lower levels of TG, TC, LDL-C, HDL-C, APOA1, and APOB (P < 0.05), and significantly higher levels of AST, Scr, and SUA (P < 0.05)." (PMID 36031606, 2022). "After adjusting for age, TG, TC, LDL-C and HDL-C, Scr, AST, ALT, ALB, APOA1, APOB, and PAB, SUA remained significantly correlated with paroxysmal AF (OR = 1.161, 95% CI 1.039–1.298, P = 0.008)." (PMID 35726017, 2022).
rectal cancer (2 papers, 2022 to 2023). A primary or metastatic malignant neoplasm that affects the rectum. "A study found that the APOB/APOA1 ratio is a specific predictor of liver metastasis in rectal cancer patients." (PMID 38067270, 2023). "This retrospective study aimed to assess the implication of apoB-to-apoAI ratio in predicting liver metastasis from rectal cancer (RC)." (PMID 34979995, 2022). "Although, another study which assessed this prognostic factor found that a high APOB/APOA1 ratio was found to predict poorer survival in patients with metastatic CRC to the liver, as well as in patients with advanced rectal cancer." (PMID 38067270, 2023).
renal carcinoma (2 papers, 2018 to 2020). A carcinoma arising from the epithelium of the renal parenchyma or the renal pelvis. "In line with this, immunoreactivity for apoA-I, apoB, or SR-BI was associated with the differentiation of renal carcinomas into ccRCC as well as with tumor grade (apoA-I and apoB) or tumor stage (apoB)." (PMID 30173145, 2018). "APOBEC3G, a member of the Apolipoprotein B mRNA editing enzyme-catalyzed polypeptide (APOBEC) family, was found to be overexpressed in renal carcinoma tissues and cell lines, consistent with our results." (PMID 33488680, 2020). "First, the immunochemical investigation of apoA-I and apoB in renal carcinomas revealed that ccRCCs store lipoproteins rather than lipids per se." (PMID 30173145, 2018).
Renal insufficiency (2 papers, 2017 to 2022). A reduction in the level of performance of the kidneys in areas of function comprising the concentration of urine, removal of wastes, the maintenance of electrolyte balance, homeostasis of blood pressure, and calcium metabolism. "The apolipoprotein B/A-I ratio was significantly different according to coronary artery calcification in the participants with normal kidney function, but in the participants with mild renal insufficiency, it was not different." (PMID 28957410, 2017).
rheumatic diseases (2 papers, 2020 to 2024). "There is increasing evidence to show that the atherogenic ApoB/ApoA1 ratio is an independent prospective predictor of cardiovascular events both in the general population and in patients with rheumatic diseases." (PMID 32298352, 2020).
sleep disorder (2 papers, 2020 to 2024). A change from the patient's baseline sleeping pattern, in the hours slept and/or an alteration/dysfunction in the stages of sleep. "Furthermore genes associated with gamma-aminobutyric acid (GABRA2, GABRB) have been implicated in sleep disorders including ApoB." (PMID 32000760, 2020). "Apolipoprotein B has a negative causality with neutrophil cell count and sleeping disorders including trouble falling or staying asleep, or sleeping too much." (PMID 39043735, 2024). "Apolipoprotein B can control sleeping disorders and also neutrophil cell count." (PMID 39043735, 2024).
sudden sensorineural hearing loss (2 papers, 2013 to 2024). Sensorineural hearing loss which develops suddenly over a period of hours or a few days. "Total cholesterol, low density lipoprotein cholesterol and apolipoprotein B concentrations may be important factors in the pathogenesis of sudden sensorineural hearing loss, and should be assessed during the investigation of patients with this condition." (PMID 23819577, 2013).
synucleinopathies (2 papers, 2015 to 2025). "We have shown the ability of the ApoB peptide (ApoB11) to transport an ASO sequence targeted to aSyn for a systemic therapy for synucleinopathies that has proven effective in synucleinopathy models of Parkinson’s disease and Dementia with Lewy Bodies." (PMID 41282154, 2025).
systemic inflammatory response syndrome (2 papers, 2012 to 2016). SIRS is a serious condition related to systemic inflammation, organ dysfunction, and organ failure. "It has been shown that serum ApoB levels are significantly reduced in patients suffering from a systemic inflammatory response syndrome with associated MOF31." (PMID 26902749, 2016).
Tobacco use disorder (2 papers, 2022 to 2023). "We also observed nominal associations between rare variants in KCNQ1 and substance use disorders (P = 2.4 × 10–4), and APOB and tobacco use disorder (P = 1.1 × 10–3)." (PMID 35590255, 2022).
viral hepatitis (2 papers, 2016 to 2024). An acute or chronic inflammation of the liver parenchyma caused by viruses. "Our results of the metabolomic analysis showed that hsa-miR-122-5p levels had a direct association with small VLDL, IDL, large LDL subfractions, and apoB levels, indicating that hsa-miR-122-5p is connected with cholesterol levels in a viral hepatitis-free human population." (PMID 27917915, 2016).
acute kidney injury (1 paper, 2021). Sudden and sustained deterioration of the kidney function characterized by decreased glomerular filtration rate, increased serum creatinine or oliguria. "However, it is not clear whether the serum Lp(a) level and ApoB/ApoA-Ι ratio pre-PCI are correlated with the prevalence of contrast-induced acute kidney injury (CI-AKI)." (PMID 34627286, 2021).
alcoholic hepatitis (1 paper, 2022). Acute hepatitis resulting from ingestion of alcohol. "In the report of LP-Z in alcoholic hepatitis, LP-Z expressed as the ratio of LP-Z over VLDL + LDL apoB predicted a worse 90-day survival taking account of the MELD score." (PMID 35268313, 2022).
alcoholism (1 paper, 2015). "Best example of gene polymorphisms is apolipoprotein genes such as ApoB, ApoC111, ApoE, X2 of ApoB, and S2 of ApoCIII which find association with alcoholism and cardiovascular disorders." (PMID 25949827, 2015).
Arthralgia (1 paper, 2020). "In seropositive arthralgia patients, HDL was lower while TC, TC/HDL ratio, triglycerides, ApoB, SCORE and QRISK3 were overall higher compared to the seronegative controls." (PMID 32745151, 2020).